HSDL1 (hydroxysteroid dehydrogenase like 1)
Synonyms: SDR12C3
Tractability: PROTAC: ubiquitination databases record sites on it; its protein half-life has been measured.
Gene: Protein-coding gene on chromosome 16 (84,122,141 to 84,145,212, reverse strand). Ensembl gene ENSG00000103160.
Subcellular location: Mitochondrion
Subcellular location (Human Protein Atlas): Mitochondria; Intermediate filaments; Vesicles
Gene Ontology:
Molecular function: protein binding; steroid dehydrogenase activity
Cellular component: mitochondrion
Genetic constraint (gnomAD): Loss-of-function variants: 24 observed, 28.25 expected, observed/expected ratio (o/e) 0.85, 90% interval 0.61 to 1.2. The synonymous counts are far from expectation, so gnomAD's model fits this gene poorly and the ratio says little. Missense variants: 486 observed, 427.36 expected, observed/expected ratio (o/e) 1.14, 90% interval 1.05 to 1.23. Synonymous variants: 215 observed, 159.37 expected, observed/expected ratio (o/e) 1.35, 90% interval 1.21 to 1.51.
Homologues: Orthologues: chimpanzee HSDL1 (99% identical), macaque HSDL1 (99% identical), dog HSDL1 (93% identical), pig HSDL1 (91% identical), mouse Hsdl1 (88% identical), rabbit HSDL1 (88% identical), rat Hsdl1 (85% identical), zebrafish hsdl1 (51% identical), tropical clawed frog hsdl1 (49% identical), Drosophila melanogaster CG13284 (38% identical), Drosophila melanogaster CG31810 (37% identical), Drosophila melanogaster CG31809 (37% identical), and 2 more. Paralogues in human: HSD17B12 (39% identical), HSD17B3 (31% identical), BDH1 (20% identical), HSD17B6 (20% identical), RDH16 (19% identical), HSD17B13 (19% identical), SDR16C5 (18% identical), RDH12 (17% identical), HSD17B11 (17% identical), RDH10 (17% identical), RDH5 (17% identical), HSD11B2 (16% identical), and 13 more.
Diseases named in the same sentence as HSDL1 in open-access papers:
HSDL1 is named in the same sentence as 2 diseases in open-access papers, as found by Europe PMC text mining. Sharing a sentence is not in itself a finding about the gene and the disease. The quoted sentences say what the papers report.
prostate carcinoma (1 paper, 2021). A carcinoma that arises from epithelial cells of the prostate gland. "In situ hybridization indicated that the expression of HSDL1 was higher in prostate cancer than that in normal prostate tissue." (PMID 34615913, 2021).
HSDL1 also shares sentences with these, for which no sentence is quoted: ovarian carcinoma (1 paper).